MMP9 (matrix metallopeptidase 9)
Diseases named in the same sentence as MMP9 in open-access papers (continued):
Sharing a sentence is not in itself a finding about the gene and the disease.
tumor (continued). "In the literature, MMP-2 and MMP-9 are frequently implicated in the development and expansion of tumor cells in bone metastasis." (PMID 39063556, 2024). "As RANTES/CCL5 has been previously linked to MMP9 expression and tumor cell migration, we confirmed induction of CCL5 expression using ELISA." (PMID 39286811, 2024). "As MMP9 has been linked to tumor cell invasion and migration we examined MMP9 expression using ELISA." (PMID 39286811, 2024). "MMP9 overexpression is significantly associated with higher clinical stage, larger tumor size, and poorer prognosis in BC patients." (PMID 38438469, 2024). "IL-10 has been associated with inhibiting neovascularization and tumor metastasis by downregulating the synthesis of VEGF, IL-1β, TNF-α, IL-6, and MMP-9 in tumor-associated macrophages and natural killer (NK) cell-dependent mechanisms, respectively." (PMID 38672182, 2024). "Affects tumor cells in a chemotactic and chemokinetic manner and causes elevated MMP‐9 production and activity." (PMID 39346791, 2024). "Jiang and co-authors reported that the overexpression of MMP-2 and MMP-9 in cancer cells was linked to poor survival, lymph node metastasis, and larger tumor size." (PMID 39199694, 2024). "Elevated MMP9 levels are consistently linked to more aggressive tumor behavior, advanced disease stages, and poorer patient outcomes." (PMID 39664453, 2024). "It has been described that this mechanism depends on the presence of MMP9 (matrix metalloproteinase 9), an enzyme secreted by tumor cells and tumor-associated stromal cells, which plays a critical role in degrading the extracellular matrix." (PMID 39796646, 2024). "After establishing MMP9’s role as a potential biomarker of adherent VS, we next sought to provide mechanistic insight into the function of tumor-associated MMP9 and its regulation." (PMID 38887507, 2024). "The only evidence to our knowledge that correlates pericytes and neutrophils in cancer (tumor-associated neutrophils, TANs) indicates that neutrophils are the main cellular source of pro-angiogenic MMP9, quantitatively surpassing TAMs." (PMID 39086395, 2024). "Elevated MMP-2 and MMP-9 activity is closely linked to the formation of metastatic niches, angiogenesis, and other functions within the tumor microenvironment, such as the chemotaxis of inflammatory cells and the perpetuation of an inflammatory milieu." (PMID 39684484, 2024). "In this systematic review, serum CA19-9, bilirubin, albumin, CEA, NLR, PLR, and tumour MMP9 were the only biomarkers associated with prognosis for pCCA resected with curative intent in at least two separate studies." (PMID 38398089, 2024). "The 4 h LMF exposure caused a significant increase in MMP2 and MMP9, as well as in onco-miRs miR-155, miR-210, miR-21, but a significant reduction in tumour-suppressor miRs (miR-200c and miR-126) in the metastatic PC3 cells, compared with normal PNT2 cells." (PMID 39336161, 2024). "Nevertheless, our data suggest that the increased responsiveness of tumor endothelial cells to VEGF underlies the high MMP9 expression in CD93-deficient tumors." (PMID 38441970, 2024). "Slit2 treatment further induced gene expression associated with a tumor-promoting macrophage phenotype by activating MMP-9, VEGF-a, Mrc1, Ccl19, TGF-β1, IL-10, Cd209a, and Arg1." (PMID 39456164, 2024). "Elevated serum levels of MMP9 serve as a potential diagnostic marker, reflecting the tumor’s burden and aggressiveness." (PMID 39664453, 2024). "In cancer, increased ECM stiffness often initiates EMT, closely linked with MMP-9 upregulation, thereby facilitating tumor invasion." (PMID 38693104, 2024). "MMP9’s association with inflammatory mediators throughout CRC stages hints at its broader implication in tumor-related inflammation and tissue alterations." (PMID 39664453, 2024). "Among these proteases, MMP-2 and MMP-9 are frequently associated with tumor cell migration, invasion, and metastasis." (PMID 39594778, 2024).
tumor (continued). "MMP‐9, implicated in extracellular matrix breakdown, plays a pivotal role in tumour invasion, metastasis, angiogenesis and the regulation of the tumour microenvironment." (PMID 38506084, 2024). "This interaction is involved in the recruitment of matrix metalloproteinase 9 (MMP9)-positive tumor-associated macrophages (TAMs)." (PMID 38684596, 2024). "MMP-9 secretion has been demonstrated to be driven by c-Myc expression in tumors and tumor-associated macrophages (TAMs), despite the fact that it is not a direct transcriptional target." (PMID 39338293, 2024). "For example, TIMP-1, which inhibits MMP-9, has been reported to present pro-tumor effects and is associated with cancer recurrence and poor prognosis." (PMID 39063046, 2024). "For conditional activation, a cleavable linker for the tumor‐associated protease MMP‐9 was implemented." (PMID 39655405, 2024). "Under hypoxic conditions, tumor-associated macrophages further produce VEGF and stimulate MMP-9 secretion, collectively promoting tumor angiogenesis and invasive potential." (PMID 38542288, 2024). "Several studies highlighted that elevated level of MMP-9 is associated with higher tumor grade and reduced survival rate in patients with BC." (PMID 39351229, 2024). "Raised serum CA19-9, bilirubin, CEA, neutrophil-to-lymphocyte ratio (NLR), platelet-to-lymphocyte ratio (PLR) and tumour MMP9, and low serum albumin were most associated with poorer survival; however, the cutoff values used widely varied." (PMID 38398089, 2024). "This was attributed to the decreased infiltration of tumor-associated macrophages within the tumor microenvironment that produces matrix metalloprotease 9 (MMP-9) which is well documented to play a crucial role in the process of angiogenesis." (PMID 39367471, 2024). "Tumour cell staining > 50% for MMP9 upon immunohistochemistry (IHC) was significantly associated with reduced OS upon multivariable analysis in both studies." (PMID 38398089, 2024). "Apart from acting as an immune checkpoint for T cell control, Opn favors angiogenesis and tumor progression through M2 macrophage recruitment through the secretion of prostaglandin E2 and MMP-9 from tumor-associated macrophages." (PMID 39272810, 2024). "Apart from TAMs, other immune cells within the tumor, such as tumor-associated neutrophils and mast cells, are likewise a source of MMP-9." (PMID 38455762, 2024). "Matrix metalloproteinase-9 (MMP-9) or gelatinase B has been directly linked with tumor invasion and metastasis due to its ability to degrade collagen type IV in the ECM supporting the formation of TME." (PMID 39351229, 2024). "Through the analysis of tissue samples from 52 patients, the study reveals that higher MMP9 expression is linked to more advanced cancer stages and higher grades of tumor pathology." (PMID 39664453, 2024). "This inhibitory effect was ascribed to the promotion of apoptosis in tumor tissues and the restraint of proteins associated with tumor proliferation (ki67), metastasis (MMP-9), and angiogenesis (CD31 and VEGF) expression." (PMID 39091624, 2024). "The degradation of type IV collagen, the major structural collagen of the extracellular matrix, by MMP-2 and/or MMP-9, is often associated with tumor invasion and metastasis." (PMID 37057283, 2023). "Tumor-associated macrophages can produce matrix metalloprotease 9 (MMP9), a kind of enzyme responsible for tumor angiogenesis." (PMID 38274735, 2023). "CD8+ tumor-infiltrating lymphocytes (TILs) were also positively associated with Knosp (p = 0.002) and MMP-9 grades (p = 0.01)." (PMID 36831707, 2023). "This study evaluated the association between MMP-9 serum levels and tumor metastasis, staging, and nodal involvement." (PMID 36938194, 2023). "The metastasis of malignant tumors is frequently the main cause of tumor treatment failure, and the degradation of extracellular matrix caused by matrix metalloproteinase-9 (MMP-9) plays a key role in this process." (PMID 37765183, 2023).
tumor (continued). "In fibrosarcoma HT1080 cells, MMP9 knockdown caused increased cell adhesion and inhibited tumor cell migration." (PMID 36677584, 2023). "In other contexts, such as the tumor microenvironment, MMP9 expression is associated with a distinct subset of infiltrating myeloid cells and tumor epithelial cells." (PMID 36810514, 2023). "The interaction of LCN2 with MMP9 is associated with the invasive behaviour of several tumour cells." (PMID 37060578, 2023). "The RECK gene has been reported to encode a membrane-anchored glycoprotein that can negatively regulate MMP-2 and MMP-9 activities and is strongly associated with tumor angiogenesis and metastasis in various human cancers." (PMID 36895489, 2023). "It has been observed that the overexpression and increase in the secretion of MMP-2 and MMP-9 are associated with processes such as invasion, metastasis, and a poor prognosis, resulting in key factors in tumor progression." (PMID 38137922, 2023). "An increasing number of studies have shown that MMP9 is associated with tumor immunity, including in T-cell depletion and immune checkpoint suppression, leading to the immune escape of tumor cells." (PMID 37313408, 2023). "Dysregulation of MMP‐9, which encodes matrix metalloproteinases 9, plays a critical role in tumour invasion and progression of GC by affecting tumour microenvironment." (PMID 37118990, 2023). "In a model of colitis-associated CRC, anti-neutrophil antibodies reduced tumor size and neutrophil infiltration in the colon, as well as MMP9 mRNA expression." (PMID 36950522, 2023). "Tumor MMP-9 expression is associated with poor outcomes in OPSCC, especially in HPV-negative disease, whereas Rgp immunoexpression in inflammatory cells is associated with better disease-specific survival, which can be utilized to predict prognosis." (PMID 38248096, 2023). "In reverse, the same study showed that increased levels of MMP-9 in tumour tissue, are associated with better survival compared to decreased levels." (PMID 36982551, 2023). "MMP2 and MMP9 are strongly expressed in varying malignant tumor tissues and are strongly associated with tumor cell invasion and metastasis." (PMID 36882799, 2023). "Overexpression of MMP1 and MMP9 in solid tumors was associated with tumor invasion and metastasis have been reported." (PMID 37052818, 2023). "A reduced matrix degradation, associated to the loss of MMP9, resulted in lower tumor growth and poorer angiogenic capacity in different tumors." (PMID 37963919, 2023). "Given the key roles mediated by MMP2 and MMP9 in tumor metastasis, their association with MALAT1 and ALKBH5 was subsequently investigated." (PMID 37639643, 2023). "XH significantly reduced the expression of MMP-2 and MMP-9, strongly associated with the metastatic potential of many tumor cells." (PMID 37373500, 2023). "As observed in this study, a high expression of the MMP9 is associated with a higher chance of lymph node metastases and an advanced tumor stage." (PMID 36756017, 2023). "By examining key genes within this pathway, we found, MMP9, which encodes a zinc-dependent endopeptidase that can promote tumor growth by degrading matrix barriers, highly expressed in macrophages." (PMID 38123589, 2023). "Some proteins stored in the granules of neutrophils, such as neutrophil elastase (NE) and matrix metalloproteinase 9 (MMP-9), have been associated with tumour development." (PMID 37627581, 2023). "MMP-9 is generally associated with increased invasion, metastasis, and progression of a wide variety of tumor entities, including HNSCC." (PMID 36674806, 2023). "High expression of MMP9 is associated with human tumor invasion or metastasis, and knockdown of MMP inhibits the migration of ES cells." (PMID 36988561, 2023). "MMP-9, one of the most complex Matrix Metalloproteinase (MMPs), causes the degradation of gelatine and various types of collagen which is essential for tumor invasion and metastasis." (PMID 37697240, 2023).
tumor (continued). "CA4 can enhance the expression of MMP9 in tumor tissue by destroying immature tumor blood vessels and causing a hypoxic microenvironment that significantly promotes the release of DOX prodrugs." (PMID 37111692, 2023). "MMP9 has been confirmed as an important gene implicated in tumor invasion and metastasis through epithelial-mesenchymal transition (EMT) processes." (PMID 37415735, 2023). "APOA1 changes the phenotypic expression of the macrophages from pro-tumor (M2) to anti-tumor (M1), and blocks tumor-associated angiogenesis by downregulating MMP-9 expression." (PMID 38067270, 2023). "TNBC lung metastasis, which was positively associated with MMP9 expression in tumor tissues, was suppressed by cRGD-lipo-LGAL." (PMID 37041137, 2023). "Among them, MMP2 and MMP9 were significantly associated with tumor immune infiltrates and had good binding affinity with effective ingredients." (PMID 37565919, 2023). "Combined positivity for tumor associated neutrophils, MMP-9, IL-17, and CD105 was reported to be associated with the metastasis-prone phenotype of OSCC." (PMID 37373022, 2023). "In most cases, high MMP-9 levels in tumor tissues or serums relate to an advanced stage and high risks, and patients in these circumstances need more aggressive and rapid treatment approaches." (PMID 37175113, 2023). "NF-κB and AP-1 regulate the expression of multiple genes involved in tumor proliferation and metastasis, including those encoding cyclin D1, cyclin E, Myc, MMP-9, MT1-MMP, uPA, Snail, and ZEB1." (PMID 37894738, 2023). "A higher CAR was associated with elevated levels of VEGF, TGF-beta, and MMP-9 (markers associated with angiogenesis, immunosuppression, epithelial–mesenchymal transition, tumour invasion and metastasis)." (PMID 37829342, 2023). "In our study, MMP-9 expression along with positive nodal status and large tumor size proved to be independent factors associated with the lack of pathological response to NAC (non-responders) compared with partial responders." (PMID 37511057, 2023). "Of the different subtypes, multiple studies have demonstrated that matrix metalloproteinase 9 (MMP9) overexpression is often associated with the aggressive nature of the tumor." (PMID 36756017, 2023). "H. pylori infection can also upregulate the expression of metalloproteinase-9 (MMP-9), an enzyme that degrades the extracellular matrix, which increases the risk of poor prognosis in tumor patients." (PMID 37325512, 2023). "MMP-3, from the stromelysin class, is also associated with tumor progression and activates MMP-9 trough partial proteolysis." (PMID 38003553, 2023). "Subsequently, we detected the protein levels of several NF‐κB signaling pathway related biomarkers and MMP9, a hallmark of tumor invasion." (PMID 34697897, 2022). "Subsequently, we detected MMP-2 and MMP-9 protein expression associated with tumor metastatic ability to explore possible mechanisms." (PMID 35936728, 2022). "Both MMP-2 and MMP-9 have been linked to tumour growth, cell death, inflammation, bone remodelling, and immunity." (PMID 35408590, 2022). "As in HCC, MMP9 detection in VX2 liver tumors is associated with rapid progression of the tumor, especially after locoregional therapies such as TACE and RFA." (PMID 35619923, 2022). "MMP-9 promotes the destruction of basement membrane and extracellular matrix, an action associated with tumour cell and secondary tumour maturation." (PMID 35151278, 2022). "It is well known that a decreased Bax/Bcl-2 ratio indicated that apoptosis was inhibited, and MMP9 was an important enzyme that degraded the extracellular matrix (ECM) during tumor metastasis and was highly associated with tumor invasion." (PMID 35991881, 2022). "In CRC, increased tumour MMP-9 expression is associated with advanced cancer stages, lymph node metastasis and reduced patient survival." (PMID 36263033, 2022).
tumor (continued). "TLM reduced TGF-β levels in NSCLC lung tumors, which was linked to PPAR-γ activation, VEGF, and MMP-9 inhibition, resulting in more nanoparticle penetration into the tumor." (PMID 35745729, 2022). "As a result of an experimental study of patients with primary early BC, higher expression of MMP9 in tumor cells was found in comparison with tumor-associated stroma and its correlation with a tumor cell proliferation index." (PMID 36293492, 2022). "Specifically, our findings demonstrated that the expression of LCN2 and MMP9 was associated with the development of main tumor types." (PMID 36211450, 2022). "The results showed that MMP-9 was significantly associated with immune checkpoints in most tumor types." (PMID 35178444, 2022). "Abnormal expression of MMP-2 and MMP-9 is associated with multiple stages of tumour growth, vascular invasion, tumour progression, and metastasis." (PMID 35498401, 2022). "As found by biomedical images, MMP9 is an extracellular matrix associated with stromal cell protein that promotes tumor progression and regulates the activity of cell adhesion molecule and cytokines." (PMID 35874525, 2022). "MAP2K5 activates MAPK7 that, in combination with MMP9, is associated with positive tumor-inducing signaling in cancer patients." (PMID 36552714, 2022). "Activation of TGF-β1 by fibroblast-associated MMP9 was found to be crucial for fibroblast-to-myofibroblast differentiation, a key step in tumor stroma formation." (PMID 35406619, 2022). "The overexpression of matrix metalloproteinase-9 (MMP-9) is associated with tumor development and angiogenesis, and hence, it has been considered an attractive drug target for anticancer therapy." (PMID 35463960, 2022). "Although all capped mRNAs require eIF4F for translation, mRNAs encoding for proteins involved in tumor invasion and metastasis (Matrix metalloproteinases 9 (MMP-9), heparanase) are exceptionally dependent on elevated eIF4F activity for translation." (PMID 36009534, 2022). "There is an association between low plasma levels of MMP9 and decreased levels of endothelial inhibitor angiostatin in terms of increased tumor growth and vascularization." (PMID 36564776, 2022). "Among all members of the MMP gene family, MMP-2 and MMP-9 are considered to be especially important in the degradation of the extracellular matrix that is associated with malignant behavior in a variety of tumor cells." (PMID 35163891, 2022). "The expression of MMP-9 was positively correlated with the markers of T cells, tumor-associated macrophages, Th1 cells, and T cell exhaustion." (PMID 35178444, 2022). "On the contrary, some studies have shown that MMP-9 overexpression in liver tissue was a risk factor for advanced T category, tumor stage and poor outcome." (PMID 36387161, 2022). "In BC, high levels of MMP9 are associated with cancer development and tumor progression, while in TNBC MMP9 promotes angiogenesis and metastasis." (PMID 36226048, 2022). "Matrix metalloproteinases MMP2 and MMP9 are implicated in tumor angiogenesis and invasion, and these processes are regulated by some genes." (PMID 35912155, 2022). "Taken together, we demonstrated that the HOXD11/FN1/MMP2/MMP9 axis was an underlying molecular mechanism promoting tumor invasion and metastasis via an EMT-like phenotype in PSCC." (PMID 36151071, 2022). "The overexpression of LCN2 and MMP9 was consistently associated with the early promoter methylation status of both genes that have been found to be partially methylated in most tumor types." (PMID 36211450, 2022). "They upregulated expressions of MMP2 and MMP9, which are extracellular membrane-degrading enzymes associated with tumor aggressiveness." (PMID 36230547, 2022). "The decrease in MMP-9 in plasma causes down-regulation of angiostatin synthesis, which results in tumor growth and vascularization." (PMID 36776395, 2022).